RNU6-798P (RNA, U6 small nuclear 798, pseudogene)
Gene: Small nuclear RNA gene on chromosome 9 (97,192,923 to 97,193,025, reverse strand). Ensembl gene ENSG00000252721.
Homologues: Orthologues: macaque U6 (96% identical), dog U6 (68% identical), mouse Gm54642 (59% identical), mouse Gm22279 (57% identical), rat LOC120101210 (56% identical). Paralogues in human: RNU6-714P (92% identical), RNU6-316P (91% identical), RNU6-55P (91% identical), RNU6-821P (90% identical), RNU6-954P (90% identical), RNU6-1193P (88% identical), RNU6-1269P (88% identical), RNU6-368P (88% identical), RNU6-538P (88% identical), RNU6-1320P (87% identical), RNU6-599P (87% identical), U6 (87% identical), and 1288 more.